JAK1 (Janus kinase 1)
Diseases named in the same sentence as JAK1 in open-access papers (continued):
Sharing a sentence is not in itself a finding about the gene and the disease.
tumor (continued). "Since the JAK1/2 kinase family has been reported to mediate PD-L1 expression on extracellular stimulation in tumor cells, we first investigated the effects of ruxolitinib (a JAK inhibitor) on the expression of PD-L1 in pemetrexed-treated CL1-5 and CL141 cells." (PMID 33243934, 2020). "These included the canonical JAK1 p.G1097D in the primary tumor at a 0.93% VAF, which was then enriched in the PDTX, reaching a 63.2% VAF in passage T1." (PMID 32560455, 2020). "There are abundant high‐frequency mutations of proteins in the INF‐γ signaling pathway in tumor cells of immunocheckpoint‐resistant patients, such as IFN‐γ receptor 1 and 2, JAK1/2, and IRF‐1 (Interferon regulator factors 1)." (PMID 32875727, 2020). "A previous study suggested that JAK1 mediates many immune regulatory processes, including those that are involved in tumor-driven immune escape, cancer immunosuppression, and sustained inflammation in the tumor microenvironment." (PMID 33323549, 2020). "Restored expression of PD-L1 in IFNγR2- and Jak1-mutant tumor cells re-established the progressive growth kinetics comparable to WT tumors." (PMID 32001684, 2020). "Co-treatment with genistein and the JAK1 pathway inhibitor GLPG0634 (1 mg/kg) or the Akt pathway inhibitor MK-2206 (1 mg/kg) had an enhanced inhibitory effect on tumor growth in comparison with matched control groups (P<0.01)." (PMID 32276266, 2020). "The CIBERSORT and TIMER databases were used to analyze the correlations between JAK1 and tumor-infiltrating immune cells." (PMID 33323549, 2020). "IFN-γ is involved in anti-viral and anti-tumor immune responses by triggering transcription of several genes such as Ido-1 which is transcriptionally regulated by IFN-γ through activation of Jak-1 and STAT-1 but also NF-κB." (PMID 32384638, 2020). "Further statistical analysis showed that the expression levels of miR-26a and JAK1 mRNA in HCC tumor tissues were positively correlated (P < 0.001)." (PMID 32732872, 2020). "Using total protein from HCC827 xenograft tumour tissues, we found that Afatinib inhibited the phosphorylation of JAK1,2, STAT3, and FAK, the protein expression of LYVE-1, VEGFR2, VEGFR3, VEGFC, VEGFA, and CCR7." (PMID 31892990, 2020). "Consistent with the RNA expression data, results indicated that the protein expression of JAK1 was lower in LUAD tissues than in normal tissues, and was negatively associated with tumor grade." (PMID 33323549, 2020). "In BC, IL-7 promotes tumor growth by activating the JAK1/3-STAT5 and PI3K/AKT pathways, while the IKZF1 gene plays important regulatory roles in lymphogenesis." (PMID 33164640, 2020). "To validate our initial in vitro CRISPR/Cas9 screen we exposed IFNγR2- and Jak1-mutant tumor cells to activated 2 C/Rag2–/– T cells to evaluate lysis." (PMID 32001684, 2020). "It has been demonstrated that TNF‐α as the critical trigger along with increased activation of JAK1/STAT1 plays a crucial role in tumor cell proliferation and invasiveness." (PMID 32677756, 2020). "Loss-of-function mutations in JAK1 or JAK2 abrogates response to IFN-γ, desensitizing tumor cells to IFN-induced growth inhibition." (PMID 32111080, 2020). "JAK1 was positively associated with tumor-infiltrating immune cells, and the results of CIBERSORT analysis suggested that JAK1 was correlated with monotypes and M1 macrophages." (PMID 33323549, 2020). "To determine if the spontaneous tumor control was dependent upon adaptive immunity, we inoculated Rag2–/– mice with WT, IFNγR2-, or Jak1-mutant tumor cells and tracked tumor growth." (PMID 32001684, 2020). "We first measured PD-L1 expression on the host and tumor compartments in WT, IFNγR2-, and Jak1-mutant tumors following implantation in vivo." (PMID 32001684, 2020). "In this context, genetic knockdown of IL-6 or JAK1/2 decreased tumor cell growth in vivo and/or in vitro." (PMID 32365499, 2020). "Many of the differentially expressed genes found were shared between IFNγR2- and Jak1-mutant tumor cells." (PMID 32001684, 2020).
tumor (continued). "As far as tumor-related factors are concerned, target antigen-positive resistance mainly results from tumor mutations such as those in PTEN and JAK1/JAK2, and this mechanism requires further investigation." (PMID 31824840, 2019). "The evidence indicates that JAK1 works as either an oncogene or a tumor suppressor under certain conditions or cell contents." (PMID 31790361, 2019). "Treatment of ALK− ALCL tumor bearing mice carrying JAK1 and STAT3 mutations with ruxolitinib, a JAK1/JAK2 inhibitor, led to inhibition of tumor formation, which demonstrates the therapeutic potential of targeting the JAK1/STAT3 pathway." (PMID 31684088, 2019). "Loss of JAK1 reduced JAK-Signal transducer and activator of transcription signaling in tumor cells—resulting in tumor resistance to the T-cell effector molecule interferon—and suppressed T-cell activation by impairing antigen presentation." (PMID 30837996, 2019). "In summary, our study provides insights into understanding the potential role of JAK1 mRNA in tumor immunology and its prognostic value." (PMID 31790361, 2019). "JAK1/2 inhibition in tumor cells of ruxolitinib treated mice was efficient, since activation of the downstream effector STAT3 was almost absent after tyrosine kinase inhibitor treatment." (PMID 31407334, 2019). "Activation of the JAK1-dependent interferon gamma (IFNγ) signaling pathway is known to have direct effects on tumor cells, impacting numerous cell programmes including growth, apoptosis, proliferation, differentiation and migration." (PMID 31552026, 2019). "By using human tumor samples and experimental mouse models, we show that JAK1/2 are activated in K‐RAS‐driven lung AC and promote tumor growth and progression by establishing a protumorigenic TME." (PMID 31407334, 2019). "IFNyR surface expression on TC1 and B16F10 tumor cells and Jak1 and Jak2 expression was similar in all culture conditions (respectively)." (PMID 31196219, 2019). "This discrepancy can be interpreted as the result of a higher cell turnover in early tumorigenesis or by a tumor‐compensatory mechanism upon JAK1/2 inhibition present at early tumor stages." (PMID 31407334, 2019). "Accordingly, administration of the JAK1/2 selective tyrosine kinase inhibitor ruxolitinib reduced proliferation of tumor cells and effectively reduced tumor progression in immunodeficient and immunocompetent mouse models of K‐RAS‐driven lung AC." (PMID 31407334, 2019). "PRP induced tumor cell apoptosis by inhibiting the Jak1–Stat3 pathway and by activating Caspase-3 and Caspase-8 to increase the Bax/Bcl-2 ratio." (PMID 29735884, 2018). "The functionally-verified immune-resistance genes that were disproportionally mutated in hot tumours included those involved in antigen presentation (B2M and HLA-A), apoptosis (CASP8) and interferon signalling (JAK1)." (PMID 30104673, 2018). "In the MC38 model, the significant antitumor activity of anti-PD-1 against the parental was lost in JAK1/2 and B2M KOs; in these KO sublines, CyTOF analysis revealed that anti-PD-1 therapy was unable to change tumor CD8 T-cell infiltration." (PMID 30400822, 2018). "The rare occurrence of JAK1 frameshifts in prostate or urinary cancer can be explained in part by the rarity of MSI in these tumor types." (PMID 29121062, 2017). "All of these alterations in addition to gene mutations would predispose to JAK1/JAK2 inactivation and IFNγ-resistance in tumours if put under selective pressure by the immune system." (PMID 28561041, 2017). "To study the functional effects of JAK1 frameshifts on tumor phenotype, we compared mRNA expression profiles of JAK1 frameshift and JAK1 wild-type samples from MSI-H UCEC samples in the TCGA dataset." (PMID 29121062, 2017). "We investigated the correlation of the IFNγ response signature with JAK1 expression since expression is reduced in cell lines and tumor samples with a JAK1 frameshift." (PMID 29121062, 2017).
tumor (continued). "This analysis suggested that the effects of JAK1 frameshifts on IFN signaling were likely tumor cell intrinsic whereas decreased expression of activated immune cell genes was likely cell extrinsic." (PMID 29121062, 2017). "The subpopulation of Ma-Mel-61h-JAK1 transfectants demonstrated de novo HLA class I surface expression after IFNγ-treatment, resulting in detection of the previously ignored tumour cells by autologous CD8+ T cells." (PMID 28561041, 2017). "Consistent with the TCGA UCEC tumor samples, JAK1 and IRF9 were the first and third most significantly downregulated genes, respectively (tab CCLE)." (PMID 29121062, 2017). "From these data, we conclude that homozygous loss of JAK1 leads to loss of the IFNγ response gene set, consistent with a role for JAK1 as a tumor suppressor in this context." (PMID 29121062, 2017). "The in vitro and in vivo inhibition of JAK1/2 by ruxolitinib abolished the macrophage-induced tumor proliferative effects and decreased MYC expression." (PMID 29207662, 2017). "JAK1-dependent STAT3 activation has been reported to promote tumor cell cycling, survival, and invasiveness, enhance telomerase activity and modulate angiogenesis." (PMID 28720093, 2017). "Here, IL10 knockout not only decreased JAK1 activity but also inhibited Src phosphorylation, suggesting that IL10 from cancer cells or the tumor microenvironment increases JAK1 and Src activities." (PMID 26956044, 2016). "In a male-predominant hepatocellular carcinoma model, 17β-estradiol (E2) repressed alternative macrophage activation and tumor growth through the inhibition of Janus activated kinase-1 (JAK1) and STAT6 phosphorylation." (PMID 27886105, 2016). "Diaphragm specific force was significantly reduced in tumor-bearing mice receiving standard chow; however, treatment with the JAK1/3 inhibitor completely prevented diaphragm weakness." (PMID 26864813, 2016). "Provided the relatively low incidence of the single gene mutations, clonal mutations (detected in >20% of tumor population) were grouped into the JAK/STAT (IL7R, JAK2, JAK1, CRLF2 mutations and CRLF2-rearrangements) and RAS/RTK (FLT3, KRAS, NRAS) pathways." (PMID 26883104, 2016). "Ruxolitinib, an FDA approved JAK1/2 pharmacological inhibitor, targets proinvasive tumour microenvironment modifications by transiently inhibiting human CAF contractility." (PMID 26667266, 2015). "Taken together, these data indicate that pharmacological antagonism of JAK1–STAT signalling inhibits growth of primary SS tumour cells." (PMID 26415585, 2015). "It's well-known that activation of STAT3 culminates in the transcription of its target genes and that EGF signaling relevant to tumor growth and metastasis is partially mediated by JAK1/2 phosphorylation." (PMID 25915156, 2015). "Intriguingly, in vivo blocking of IL-6/STAT3 signalling by the JAK1/2 inhibitor ruxolitinib in human LNCaP xenografts showed significantly enhanced tumour size and weight." (PMID 26198641, 2015). "We show that, although AZD1480 has the ability to delay tumor growth and prolong survival of MO4-tumor bearing mice, the inhibition of JAK1/2 has detrimental effects on several aspects of the immune system of these mice." (PMID 25149535, 2014). "AZD1480, a pharmacological JAK1/2 inhibitor, exhibits anti-tumor potency in multiple adult malignancies." (PMID 23531921, 2013). "Selective Jak1 and Jak2 inhibitors can also inhibit Il-6/Stat3 signaling and concomitantly reduce tumor growth in xenograft models." (PMID 23520493, 2013). "The authors suggested that JAK1 may act as a tumor suppressor, and that deletion of JAK1 activates the HIF1α pathway." (PMID 41520505, 2026). "JAK1 and JAK3 were more expressed in the tumor stage than patch and plaque stage MF, suggesting that JAK1 and JAK3 could play a crucial role in MF pathogenesis, progression, and prognosis." (PMID 41806757, 2026). "Mechanistically, UBA1 facilitates STUB1-mediated proteasomal degradation of JAK1 in tumor cells." (PMID 39540840, 2025).
tumor (continued). "As expected, tumor cells with high UBA1 expression showed lower JAK1 and MHC-I expression." (PMID 39540840, 2025). "To further investigate whether I3A increased MHC‐I expression via JAK2‐STAT3 signaling axis, we used Ruxolinitib, a JAK1/2 inhibitor, to treat tumor cells together with I3A." (PMID 40583248, 2025). "Our results reveal a previously unexplored tumor-promoting mechanism of JAK1 signaling." (PMID 39744421, 2025). "Mutations in genes like JAK1 and JAK2 may disrupt normal immune responses, contributing to the tumor’s ability to metastasize and resist therapies." (PMID 39925800, 2025). "In addition, the expression of STING and JAK1 in vascular endothelial cells was positively associated with the infiltration of CD8+ T cells, activated DCs, and M1 macrophages in the tumor microenvironment of pancancers." (PMID 39817453, 2025). "Given the essential role of the JAK1/2 pathway in the efficacy of PD-L1 blockade therapy, we conducted further investigations to explore its potential influence on how PD-L1 blockade therapy affects the tumor vascular structures." (PMID 40370455, 2025). "Tumor‐specific factors, such as the immune microenvironment, immune evasion mechanisms, tumor aneuploidy, and the presence of specific mutations (e.g., BRCA1/2, PTEN, PBRM1, or JAK1), all contribute to ICI treatment outcomes, highlighting the necessity for a more comprehensive analysis of the TME." (PMID 40874420, 2025). "In NSCLC, activation of the JAK1/STAT3 pathway is considered to be crucial for tumor progression." (PMID 39209829, 2024). "CTDSPL2 may potentially affect T cell infiltration in tumors via JAK1, as previous research has demonstrated the influence of JAK1 on the tumor microenvironment." (PMID 39209829, 2024). "In addition, increased LA in TME upregulated METTL3 in tumor-infiltrating myeloid cells (TIMs) and enhanced Janus kinase 1(JAK1) protein translation efficiency and subsequent transcription activator 3(STAT3) phosphorylation via the m6A-YTHDF1 axis in CRC." (PMID 39033180, 2024). "Tumor cells stimulate osteoclasts to release the ligand interleukin (IL)-19 for the IL receptor 20 subunit β (IL-20RB), which then triggers IL-20RB-expressing tumor cells to initiate downstream JAK1/STAT3 signaling." (PMID 39512767, 2024). "Notably, we observed JAK1, JAK2, STAT3 were all located in ATC tumor cells, suggesting a crucial role of JAK1/2-STAT3 activation in maintaining malignant features of ATC tumor cells." (PMID 38336839, 2024). "In addition, tumor-derived exosomal miR-6794-5p promoted M2 polarization and the secretion of IL-10 by macrophages by activating the JAK1/STAT3 pathway, ultimately promoting tumor malignancy." (PMID 38521953, 2024). "JAK1 and JAK2 genes encode signal transducers that respond to IFNγ by increasing antigen presentation, producing chemokines to attract T-cells, and triggering tumour cell apoptosis." (PMID 38552610, 2024). "Their findings revealed that missense mutations in Janus kinase 1 (JAK1) could enhance or decrease the activity of IFN‐γ signalling pathway, thus influencing the cytotoxicity of autologous tumour‐reactive T cells within organoids." (PMID 39245957, 2024). "In LIHC, JAK1 might interact with other signaling pathways in liver cells that result in tumor suppression." (PMID 39703515, 2024). "The status whether JAK1/2-STAT3 pathway was activated in patient’s tumor tissue is considered to be an important clinical significance for Ruxo treatment." (PMID 38336839, 2024). "Additionally, it reveals that the target gene of C6 ceramide, EGR3, can effectively exert anti-tumor effects by regulating the JAK1/STAT3 signaling pathway." (PMID 38338065, 2024). "Additionally, tumor-derived exosomal-miR-6794-5p translocates to macrophages in the surrounding tumor microenvironment and activates the JAK1/STAT3 pathway by inhibiting SOCS1 expression, resulting in M2 polarization of macrophages." (PMID 38521953, 2024).
tumor (continued). "Notably, in vitro, xenograft model indicated that CAFs can facilitate tumor progression through the IL-10/JAK1/STAT3 signaling pathway." (PMID 39511039, 2024). "The binding of IFN-γ to INF-γ receptors on tumor cell membranes activates Janus Kinase 1 (JAK1) and JAK2, which are signal transducers and activators of transcription (STAT) signaling that promote the expression of IFN-related genes, including interferon regulatory factor 1 (IRF1)." (PMID 37108802, 2023). "In addition, METTL3 enhances the immunosuppressive function of tumor-infiltrating myeloid cells (TIMs) through the Jak1/STAT3 pathway by promoting Jak1 translation through the m6A-YTHDF1 axis." (PMID 37485079, 2023). "In addition to stromal STAT3, high JAK1 and JAK2 expression within the tumour cell cytoplasm was associated with reduced CSS in TNBC cases." (PMID 37199043, 2023). "In a preclinical model, IFNGR2 and JAK1 KO cells outgrew wild-type cells in a mixed tumor model." (PMID 37803324, 2023). "More importantly, there is evidence that loss-of-function mutations at JAK1 promote a lack of response to interferon gamma, leading to resistance to immunotherapy in tumor cells." (PMID 36675550, 2023). "This indicates that JAK1/EGFR-MUC1 might form a positive feedback loop to promote tumour cell proliferation and survival." (PMID 36810913, 2023). "Similarly, analysis of tumors from ipilimumab-refractory patients showed that mutations in the IFN-γ pathway genes IFNGR1/2, JAK1/2 and IRF1 inhibit the response of tumor cells to IFN-γ signaling." (PMID 37637050, 2023). "Furthermore, IFN-γ signalling can be effectively maintained within tumours through EH domain-binding protein 1-like protein 1 (EHBP1L1) shielding JAK1 from proteasomal degradation." (PMID 37503572, 2023). "Finally, we show that the translational targeting of JAK1 by miR-494-5p inhibits cancer cell migration and invasion, thereby supporting a tumor-suppressive role of miR-494-5p in the initial steps of the metastatic cascade in CRC." (PMID 38201452, 2023). "AC484 treatment reduced tumour growth in both Jak1-deficient tumours and control KPC tumours." (PMID 37794185, 2023). "In MHC-deficient HCmel12 Jak1-KO tumours, CD4+ T cells showed no changes in their migratory behaviour in the stroma and a slightly increased motility in the tumoural compartment of the invasive margin." (PMID 37316667, 2023). "In addition, silencing or mutation of genes involved in the IFN-γ pathway, such as JaK1/JaK2 and STATS, can suppress the anti-tumour effects of IFN-γ and PD-L1 expression in tumour cells." (PMID 37221594, 2023). "We suspected that the inhibitory effect of JAK1 might be responsible for the enhanced anti-tumor properties of AZD3759 compared to those of osimertinib." (PMID 34738874, 2022). "Therefore, mutations and deletions of proteins related to this pathway on tumor cells, such as JAK1 and JAK2, STAT1, and IRF1, the IFNγ receptor chain, can lead to resistance to immune checkpoint inhibitors." (PMID 36185620, 2022). "had demonstrated that JAK1 in PTC tissues was prominently upregulated than that in adjacent normal tissues, and its expression level was associated with tumor differentiation, lymph node metastasis, invasion degree, and TNM stage, and upregulated JAK1 influenced the progression of PTC." (PMID 35634509, 2022). "A previous study reported that activation of the IL-6/JAK1 pathway could drive PD-L1 Y112 phosphorylation and result in the evasion of the immune system by tumor cells." (PMID 35550592, 2022). "Therefore, we concluded that IL-6 upregulated expression of PD-L1 in tumor via the JAK1/Stat3 signaling pathway." (PMID 35550592, 2022). "Interestingly, other than the expected associations with tumour type and MSI status, the only significant predictor of IFNγ response were JAK1 LOF mutations, which predicted substantially reduced activity (β = −0.72, p = 2.48e‐07)." (PMID 35262923, 2022).